HDAC4 (histone deacetylase 4)
Diseases named in the same sentence as HDAC4 in open-access papers (continued):
Sharing a sentence is not in itself a finding about the gene and the disease.
Sepsis (13 papers, 2015 to 2024). Sepsis is defined as life-threatening organ dysfunction caused by a dysregulated host response to infection. "In conclusion, the lower activation of both glucocorticoid signaling and HDAC4-myogenin pathways by sepsis can be one of the causes of lower sepsis-induced proteolysis in the diaphragm compared to gastrocnemius." (PMID 35408999, 2022). "In sepsis-associated encephalopathy, HDAC4 is upregulated while HDAC4 inhibition suppresses Bax expression and neuronal apoptosis in vitro and in vivo." (PMID 35091534, 2022). "In sepsis, histone deacetylase 4 (HDAC4) can significantly inhibit the acetylation and secretion of HMGB1 through overexpression of TLR4/JAK/STAT1 pathway, thus inhibiting inflammation." (PMID 38156383, 2023). "In conclusion, these findings revealed that m6A methyltransferase METTL3 participated in the myocardial injury induced by sepsis via the IGF2BP1/HDAC4 axis." (PMID 35840562, 2022). "In skeletal muscle, our results show that pretreatment with the nutraceutical ameliorates the stimulatory effect of sepsis on the gene expression of the proteolytic markers atrogin-1 and MuRF1, as well as on the mRNA levels of LC3b, myogenin and HDAC4." (PMID 35795581, 2022). "Sepsis also increase HDAC4 (p < 0.05) and myogenin (p < 0.01) protein levels in gastrocnemius muscle and nutraceutical pretreatment prevented this increase." (PMID 35795581, 2022). "In this case, we targeted to explore in detail the relative mechanism of microRNA (miR)-124-3p in sepsis-induced myocardial injury via the specific protein 1/histone deacetylase 4/hypoxia-inducing factor 1α (SP1/HDAC4/HIF-1α) axis." (PMID 35091534, 2022). "Through a series of assays, we testified the mechanism of sepsis-induced myocardial injury from miR-124-3p/SP1/HDAC4/HIF-1α axis." (PMID 35091534, 2022). "Enlightened by those studies, we would wonder that whether miR-124-3p could interact with SP1, thereby affecting HDAC4/HIF-1α axis to attenuate myocardial injury in sepsis." (PMID 35091534, 2022). "Further studies are at wanting to deeply decode the miR-124-3p/SP1/HDAC4/HIF-1α axis in sepsis." (PMID 35091534, 2022). "In conclusion, the findings illustrated a role of METTL3/IGF2BP1/m6A/HDAC4 axis on sepsis-induced myocardial injury, which might provide novel therapeutic strategy for septic myocardial injury." (PMID 35840562, 2022). "It has been proved that downregulating the activated HIF-1α, the HDAC4 client transcription factor, could improve the prognosis of sepsis and relieve myocardial injury during sepsis." (PMID 35091534, 2022). "HDAC4 (histone deacetylase 4) plays an important regulatory role in sepsis and may be an effective target for sepsis treatment." (PMID 35045818, 2022). "HDAC4 has been implied as a potential treatment target for sepsis." (PMID 35091534, 2022). "All in all, it was certified that miR-124-3p interacted with SP1 to suppress HDAC4, thereby ameliorating sepsis-induced myocardial injury, which may related to the knockdown of HIF-1α." (PMID 35091534, 2022). "In addition to atrogin-1 and MuRF1 overexpression, an increase in muscle HDAC4 and myogenin has been recently reported in sepsis, and in other conditions that induce muscle atrophy such as neurological disease, disuse and aging." (PMID 35795581, 2022). "We conclude that HDAC4 might be a useful target for the treatment of sepsis." (PMID 29988587, 2018). "This interaction led to an enhancement in sepsis-induced myocardial injury, possibly related to the downregulation of hypoxia-inducing factor 1α (HIF-1α), which is the HDAC4 client transcription factor." (PMID 39062521, 2024). "The research discovered that SP1 interacts with miR-124-3p to inhibit histone deacetylase 4 (HDAC4), a promising therapeutic target for sepsis." (PMID 39062521, 2024). "It was reported that HDAC4, 5, and 7 inhibited KLF2 expression, which in turn had an important role in anti-inflammation, sepsis, and angiogenesis." (PMID 36362263, 2022).
Sepsis (continued). "In a word, miR-124-3p targeted SP1 to regulate HDAC4 and HIF-1α, thereby attenuating the pathology of sepsis-induced myocardial injury." (PMID 35091534, 2022). "Mechanically, METTL3 catalyzed m6A modification of HDAC4 mRNA, and IGF2BP1 identified the m6A site on HDAC4 mRNA and strengthened its stability, which consequently stimulates the inflammatory damage of cardiomyocytes induced by sepsis." (PMID 38112620, 2023). "miR-124-3p was lowly expressed while SP1, HDAC4, and HIF-1α were highly expressed in sepsis." (PMID 35091534, 2022). "HDAC4 (calcium signaling) and SRC (Wnt/β-catenin signaling) were also investigated because these genes were significantly altered in elderly individuals with sepsis compared with healthy elderly controls, and were not expressed at all in young adults." (PMID 26047321, 2015).
esophageal cancer (12 papers, 2016 to 2024). A primary or metastatic malignant neoplasm involving the esophagus. "The present study was performed to probe into the effect of HDAC4 on radioresistance of esophageal carcinoma (EC)." (PMID 35193602, 2022). "In addition to facilitating the deacetylation of histones and thereby regulating genetic transcription and epigenetic repression, histone deacetylase HDAC4 could be shown to promote cancer proliferation and invasion and to be associated with poor patient outcome in esophageal cancer." (PMID 34638315, 2021). "In this study, we were aimed to investigate the expression, clinical significance and biological function of HDAC4 in esophageal carcinoma (EC)." (PMID 27295551, 2016). "HDAC-4 expression is also upregulated in other cancer types including breast and esophageal cancer." (PMID 29152115, 2017). "Moreover, in terms of clinical outcomes, we found that HDAC4 expression and Sox2 expression were both negatively associated with survival in CRC, which matches a previous report that increased HDAC4 expression was associated with poor prognosis in esophageal cancer." (PMID 38473392, 2024). "The contribution of HDAC4 to EMT was observed also in esophageal carcinoma cells, but not in other cancer models, suggesting that the contribution of HDAC4 could be lineage specific." (PMID 36762207, 2023).
renal fibrosis (12 papers, 2016 to 2025). A final common manifestation of a wide variety of chronic kidney diseases characterized by glomerulosclerosis and tubulointerstitial fibrosis. "HDAC4-induced renal fibrosis was associated with renal tubular cell injury and apoptosis, promotion of pEMT, and preserving the Klotho expression at transcriptional levels." (PMID 35847036, 2022). "In summary, these results demonstrate that HDAC4 plays a critical role in promoting ferroptosis during renal fibrosis, and that its inhibition or deficiency can effectively mitigate ferroptosis and attenuate IR-induced renal fibrosis." (PMID 41282137, 2025). "We also used both the selective HDAC4 inhibitor tasquinimod and renal tubule–specific HDAC4 knockout mice to evaluate the role of HDAC4 in IR-induced renal fibrosis." (PMID 41282137, 2025). "Together, these results demonstrate that pharmacological inhibition or targeted knockdown of HDAC4 effectively reverses IR-induced renal fibrosis, partial EMT and fibroblast activation." (PMID 41282137, 2025). "Ferroptosis was clearly evident in IR-induced renal fibrosis but was substantially ameliorated in HDAC4-KO mice, as indicated by decreased ACSL4 expression and restored GPX4 levels." (PMID 41282137, 2025). "In summary, during IR-induced AKI and renal fibrosis, elevated HDAC4 promotes Foxo3a phosphorylation and cytoplasmic retention." (PMID 41282137, 2025). "To investigate the role of HDAC4 in ferroptosis during renal fibrosis, we applied either pharmacological inhibition with tasquinimod or conditional HDAC4 knockout as interventions in the unilateral IR model of chronic renal fibrosis." (PMID 41282137, 2025). "MiR-29b mimics suppressed macrophage-mediated inflammation in podocytes and attenuated HDAC4 expression, glomerular damage, and renal fibrosis." (PMID 38204237, 2024). "In this study, we utilized tasquinimod and knockout mice of HDAC4 to investigate the role of HDAC4 in the development of renal fibrosis and the mechanisms involved in a murine model of renal fibrosis induced by unilateral ureteral obstruction (UUO)." (PMID 35847036, 2022). "Our recent studies show that blocking Class IIa HDACs with MC1568 effectively inhibits the UUO-induced renal fibrosis and that HDAC4 is the most expressed class IIa isoform in the kidney." (PMID 35847036, 2022). "We demonstrated that pharmacological and genetic inhibition of HDAC4 largely attenuates renal fibrosis by suppressing several profibrotic signaling pathways, reducing renal injury, and retaining the Klotho expression." (PMID 35847036, 2022). "In summary, this study was the first to demonstrate the importance of HDAC4 in mediating the development and progression of renal fibrosis in a murine model of kidney injury following UUO." (PMID 35847036, 2022). "Cyclo-RGD truncated polymeric nanoconstructs with dendrimeric templates for targeted HDAC4 gene silencing inhibited the progression of renal fibrosis in an STZ-induced DN model." (PMID 35910382, 2022). "On this basis, we suggest that HDAC4 is a critical mediator of renal fibrosis and a potential therapeutic target for the treatment of CKD." (PMID 35847036, 2022). "Since tasquinimod was administrated 24 h after UUO when renal fibroblasts were supposed to be activated already, our results further suggest that HDAC4 not only mediates renal fibrosis but also contributes to its progression." (PMID 35847036, 2022). "To confirm the role of HDAC4 in renal fibrosis, we further examined the genetic inhibition of HDAC4 on the expression of the ECM proteins and the activation of renal fibroblasts in mice following UUO injury." (PMID 35847036, 2022). "Initial biochemical analyses showed that both tasquinimod treatment and HDAC4 knockdown significantly increased renal GSH levels and reduced MDA levels compared with fibrotic controls, suggesting that HDAC4 contributes to ferroptosis during renal fibrosis progression." (PMID 41282137, 2025).
renal fibrosis (continued). "In addition, inhibition of HDAC4 alleviated cell cycle arrest in renal fibrosis, as evidenced by p-H3 immunofluorescence and western blot analysis." (PMID 41282137, 2025). "Given that either genetic deletion of HDAC4 or late treatment with tasquinimod led to inhibition of renal injury and fibrosis, it remains obscure that the antifibrotic effect of HDAC4 inhibition is primarily due to prevention of renal tubular cell injury or inhibition of renal fibrosis." (PMID 35847036, 2022). "To date, the role and mechanisms of HDAC4 action in renal fibrosis remain undefined." (PMID 35847036, 2022). "Similarly, Pusoon Chun showed that another class IIa HDAC, HDAC4, can increase the expression of multiple profibrotic molecules by inhibiting Smad7 in renal fibrosis." (PMID 36263180, 2022). "In this study, we demonstrate that pharmacological and genetic inhibition of HDAC4 attenuates renal fibrosis and suppresses the molecular mechanisms leading to renal fibrosis, including the pEMT, fibroblast activation, and activation of the TGF-β1/Smad3, STAT3, and ERK1/2 signaling pathways." (PMID 35847036, 2022). "Besides, TGF-β/Smad3 is also revealed to suppress HDAC4 and E-Cadherin expression to accelerate renal fibrosis by miR-29 and miR-200, respectively." (PMID 32587662, 2020). "Moreover, HDAC5 and HDAC4 were both upregulated in a model of renal fibrosis and suggested to contribute to its pathogenesis." (PMID 31052182, 2019). "Piceatannol may be a beneficial therapeutic agent for treating renal fibrosis via reduction of HDAC4 and HDAC5 protein expression or suppression of the p38-MAPK signaling pathway." (PMID 27902771, 2016). "Piceatannol may attenuate renal fibrosis by inhibiting HDAC4 and HDAC5." (PMID 38929505, 2024). "In addition to its role in controlling the events leading to renal fibrosis, HDAC4 may also contribute to the injury and death of renal tubular cells." (PMID 35847036, 2022). "Due to incomplete repair in the acute phase, HDAC4 and α-SMA expression increased progressively with advancing renal fibrosis." (PMID 41282137, 2025). "However, we could not demonstrate a link between HDAC4/5 and MAPK signaling or TGF-β1/Smad signaling, nor a direct association between HDAC4/5 and renal fibrosis." (PMID 27902771, 2016).
ischemic stroke (11 papers, 2013 to 2025). A stroke disorder caused by obstruction of blood flow to the brain, due to thrombotic (local blood clot formation) or embolic (due to a blood clot or other material traveling from another site) event. "In this study, we aimed to investigate the functional roles of HDAC4 in ischemic stroke and explore the underlying mechanism." (PMID 28127553, 2017). "Adenovirus- and adeno-associated virus-mediated HDAC4 overexpression has been applied in vitro and in vivo, indicating that virus-based HDAC4 overexpression could be a potential gene therapy for ischemic stroke treatment." (PMID 30208931, 2018). "Consistently, up-regulated HDAC4 level has been documented in oligodendrocyte progenitor cells in a study based on rat models with ischemic stroke." (PMID 34526481, 2021). "HDAC4 is a unique target for the treatment of ischemic stroke compared with other HDACs, such as HDAC2." (PMID 30208931, 2018). "For example, HDAC4 features different characteristics and plays an opposite role in ischemic stroke compared with HDAC2." (PMID 30208931, 2018). "Although a variety of stem cell-based clinical trials for the treatment of ischemic stroke has been carried out or are ongoing, the therapeutic potential of HDAC4-modified stem cells remains elusive." (PMID 30208931, 2018). "Reduced HDAC4 expression is associated with blood–brain barrier (BBB) breakdown contributing to ischemia/reperfusion injury-induced infarct in ischemic stroke model rats, while increased HDAC4 expression ameliorates BBB injury, contributing to the reduced infarct volume." (PMID 37605653, 2023). "A number of microRNAs targeting HDAC4 were altered in ischemic stroke, which may also contribute to the dysregulation of HDAC4 in ischemic stroke." (PMID 30208931, 2018). "Although it is inconclusive that increasing HDAC4 expression could offer a better ischemic stroke therapy compared with HDAC2 inhibition, co-regulating HDAC4 and HDAC2 or other HDACs might have better therapeutic potential." (PMID 30208931, 2018). "The alteration and function of HDAC4 are opposite to those of HDAC2 in ischemic stroke models, indicating that increasing HDAC4 expression is a unique target for the treatment of ischemic stroke compared with inhibiting HDAC2 and other HDACs to treat ischemic stroke." (PMID 30208931, 2018). "HDAC4 expression was reduced in ischemic stroke, which may contribute to the pathogenesis of ischemic stroke by promoting neuronal death and inhibiting angiogenesis and neurogenesis." (PMID 30208931, 2018). "For example, HDAC4 is reduced in ischemic stroke model animals and oxygen-glucose deprivation (OGD)-treated neurons, while increased HDAC4 expression reduces infarct volume in ischemic stroke model animals and increases cell viability of OGD-treated neuronal cells." (PMID 30208931, 2018). "However, the expression of HDAC4 is increased in oligodendrocyte progenitor cells in the brains of ischemic stroke model rats." (PMID 30208931, 2018). "Significant alteration of microRNAs targeting HDAC4 has been detected in ischemic stroke patients and model animals, indicating that modulating microRNAs targeting HDAC4 could be a therapeutic approach." (PMID 30208931, 2018). "It suggested that the non-invasive intranasal administration of specific antagomirs could be an effective approach to increase HDAC4 expression for ischemic stroke treatment." (PMID 30208931, 2018). "Growing evidence indicates that HDAC4 is a specific target for the treatment of ischemic stroke." (PMID 30208931, 2018). "Therefore, we aim to review the dysregulation of HDAC4 in ischemic stroke and the role of dysregulated HDAC4 in the pathogenesis of ischemic stroke." (PMID 30208931, 2018). "In addition to HDAC4 levels, nuclear shuttling of HDAC4 also contributes to neuronal death and synaptic impairment in ischemic stroke." (PMID 30208931, 2018).